ZEB1 (zinc finger E-box binding homeobox 1)
Diseases named in the same sentence as ZEB1 in open-access papers (continued):
Sharing a sentence is not in itself a finding about the gene and the disease.
Fuchs endothelial corneal dystrophy (12 papers, 2016 to 2025). Fuchs endothelial corneal dystrophy (FECD) is the most frequent form of posterior corneal dystrophy (see this term) and is characterized by excrescences on a thickened Descemet membrane (corneal guttae), generalized corneal edema, with gradually decreased visual acuity. "Here, we have summarized the presence of ZEB1 and its inefficiency in the cornea that causes corneal endothelial dystrophies, particularly PPCD and FECD." (PMID 33923743, 2021). "Interestingly, ZEB1 variants cause Fuch's corneal endothelial dystrophy (FCED)." (PMID 33462143, 2021). "Mutations in ZEB1 have been shown to be implicated in endothelial dystrophies like PPCD and Fuchs Endothelial Corneal Dystrophy (FECD)." (PMID 41153364, 2025). "We also evaluated the possible pathogenicity of variants in genes known to be associated with congenital or childhood-onset monogenic corneal endothelial dystrophies (i.e., GRHL2, ZEB1, and OVOL2)." (PMID 40225920, 2024). "Although other mutations within the ZEB1/TCF8 locus and TCF4 trinucleotide repeats are associated with Fuchs’ dystrophy, only the Col8a2 missense mutant mouse has successfully recapitulated its key features." (PMID 34100716, 2021). "Also, a recent paper finds that missense substitutions in the ZEB1 protein are associated with Fuchs endothelial corneal dystrophy (FECD) and keratoconus, whereas truncated ZEB1 mutations result in PPCD." (PMID 33923743, 2021). "Similarly, variants in ZEB1, COL8A2, TCF4, FEN1, AGBL1, and LOXHD1 all cause Fuchs endothelial corneal dystrophy (FECD), while the age of onset may vary." (PMID 31555324, 2019). "Although Fuch’s corneal endothelial dystrophy (FECD) has not been formally linked to the PPCD3 locus, missense mutations in ZEB1 have been associated with this condition." (PMID 27310661, 2016).
liver fibrosis (12 papers, 2012 to 2025). "The present study also supports that the blockade of ZEB1 nuclear translocation by polydatin is a novel strategy for attenuating EMT in liver fibrosis associated with high fructose consumption." (PMID 33058500, 2020). "Inhibiting the nuclear translocation of ZEB1 by PD may be a new strategy to ameliorate EMT of liver fibrosis associated with high-fructose diet." (PMID 35186191, 2022). "The suppression of ZEB1 nuclear translocation by polydatin may be a novel strategy for attenuating the EMT in liver fibrosis associated with high fructose diet." (PMID 33058500, 2020). "Therefore, we speculated that fructose‐induced up‐regulation of p‐STAT3 may transfer into the nucleus to recruit on ZEB1 promoter, causing ZEB1 nuclear translocation in rat liver fibrosis." (PMID 33058500, 2020). "Suppression of the ZEB1/PIK3R3 axis reduces hepatic fibrosis by inhibiting its antifibrotic- effect." (PMID 39773634, 2025). "A study on the efficacy of human AMSCs amniotic mesenchymal stem cell-derived extracellular vesicles (AMSC-EVs) in treating hepatic fibrosis revealed that AMSC-EVs delivered miR-200a into hepatocytes suppressing ZEB1/PIK3R3 axis." (PMID 39773634, 2025). "To the best of our knowledge, we firstly find that ZEB1 nuclear translocation plays an essential role in fructose‐induced EMT in liver fibrosis by targeting survivin to activate TGF‐β1/Smad signalling." (PMID 33058500, 2020). "In conclusion, this study demonstrates that fructose causes ZEB1 nuclear translocation to decrease miR‐203 expression, and then target survivin to activate TGF‐β1/Smad signalling, developing the EMT in liver fibrosis." (PMID 33058500, 2020). "Liver fibrosis cells are more mesenchymal in character, with increased Snail1, Zeb1 and Zeb2 mRNA expression and decreased E-cadherin expression." (PMID 23226767, 2012). "Zeb1 also plays a role in EMT in liver fibrosis and its inhibition reduce the EMT." (PMID 41162876, 2025). "During liver fibrosis, ZEB1 has been shown to exhibit an upward trend." (PMID 41252548, 2025). "Another study revealed that ZEB1 could regulate the Wnt/β‐catenin pathway to act on insubstantial hepatic stellate cells and liver fibrosis." (PMID 39686556, 2024). "ZEB1 nuclear translocation triggered by fructose, as a switch, may suppress miR‐203 expression to cause the EMT in liver fibrosis." (PMID 33058500, 2020). "ZEB1 as a transcription factor suppresses the transcription of miR‐203 in human cancer cells, thus, we subsequently evaluated the effect of ZEB1 on miR‐203 low expression in fructose‐induced liver fibrosis." (PMID 33058500, 2020). "ZEB1 nuclear translocation inhibition with high miR‐203 expression may be the predictor of good prognosis in patients with liver fibrosis." (PMID 33058500, 2020). "In addition, ZEB1 induces TGF‐β1 expression in dimethylnitrosamine‐induced liver fibrosis of rats." (PMID 33058500, 2020). "Additionally, we found that polydatin suppressed ZEB1 nuclear translocation to increase miR‐203 expression, and then down‐regulated survivin to block TGF‐β1/Smad signalling activation, resulting in the alleviation of fructose‐caused EMT and liver fibrosis." (PMID 33058500, 2020). "Thus, ZEB1 nuclear translocation inhibition with high miR‐203 expression may be a predictor of good prognosis in patients with liver fibrosis." (PMID 33058500, 2020). "Studies have shown that ZEB1 is involved in the progression of fibrosis, and fructose promotes EMT through up-regulation of ZEB1 expression, thus inducing liver fibrosis." (PMID 37138491, 2024). "Polydatin protects against fructose‐induced hepatocyte EMT by suppressing ZEB1 nuclear translocation to up‐regulate miR‐203 expression and block survivin‐activated TGF‐β1/Smad signalling, exhibiting the potential anti‐liver fibrosis activity." (PMID 33058500, 2020).
liver fibrosis (continued). "In this study, we found that ZEB1 nuclear translocation was sufficient to decrease miR‐203 expression, this new action as a suitable alternative for targeting survivin‐activated TGF‐β1/Smad signalling in fructose‐driven EMT and liver fibrosis." (PMID 33058500, 2020). "Polydatin antagonized ZEB1 nuclear translocation to up‐regulate miR‐203, subsequently blocked survivin‐activated TGF‐β1/Smad signalling, which were consistent with its protection against fructose‐induced EMT and liver fibrosis." (PMID 33058500, 2020). "However, whether polydatin inhibits ZEB1 nuclear translocation to augment miR‐203 and block survivin‐activated TGF‐β1/Smad signalling in the alleviation of fructose‐induced EMT and liver fibrosis remains mostly unexplored." (PMID 33058500, 2020). "Moreover, polydatin represses ZEB1 nuclear translocation to increase miR‐203 expression, subsequently, block survivin‐activated TGF‐β1/Smad signalling, attenuating fructose‐induced EMT in liver fibrosis." (PMID 33058500, 2020).
lymphoma (12 papers, 2011 to 2025). A malignant (clonal) proliferation of B- lymphocytes or T- lymphocytes which involves the lymph nodes, bone marrow and/or extranodal sites. "MYC is linked to apoptosis and lymphoma whereas ZEB1 and CEBPB are enhancer binding proteins." (PMID 28765546, 2017). "Expression of ZEB1 in MCL cells also enhanced their lymphoma spheroid growth potential and increased their resistance to Bortezomib – suggestive of a cancer stem cell promoting role for ZEB1 in MCL." (PMID 37600794, 2023). "In hematologic malignancies, Zeb1 has variably been reported as either a tumor suppressor (in Sézary syndrome and adult T cell leukemia/lymphoma) or an oncogene (in mantle cell lymphoma)." (PMID 33108352, 2021). "Within the context of cancer, irregular expression of ZEB1 has been found in a multitude of human cancers including breast, pancreatic, colon, gastric, lung, uterine, liver, lymphoma, and brain cancers." (PMID 32309604, 2018). "The higher Zeb1 expression levels in malignant lymphomas suggest its involvement during B cell differentiation either at early stages or after BCR activation." (PMID 28107180, 2017). "However, ZEB1 acts as a tumor suppressor in adult T-cell leukemia/lymphoma." (PMID 22190929, 2011). "TGF-β induces the expression of Smad7 in the murine interleukin-2 (IL-2)-dependent T-lymphoma cell line CTLL2, which has high expression of the transcription factor ZEB1 and low or no expression of Smad7." (PMID 32888405, 2020).
pancreatic adenocarcinoma (12 papers, 2011 to 2025). "We next analyzed associations between VIP and ZEB1 expression in the human stomach, colon, esophageal, and pancreatic adenocarcinoma cell lines from the CCLE (cancer cell line encyclopedia) using the DepMap resource." (PMID 37444395, 2023). "Up regulation of Zeb-1 and Jagged 1 has been associated with the aggressiveness of pancreatic adenocarcinoma resulting in increased Notch signaling." (PMID 21909380, 2011). "Studies have found that the overexpression of CXCR4 and ZEB1 genes in pancreatic adenocarcinoma (PAAD) tissues is regulated by circUBAP2." (PMID 40034598, 2025). "Normalized mRNA expression data from TCGA studies of breast, prostate, lung, colorectal and pancreatic adenocarcinomas was downloaded for ZEB1, ZEB2, SNAI1, SNAI2, TWIST1, FOXQ1 and FOXC218,19." (PMID 31780722, 2019). "circUBAP2 modulates pancreatic adenocarcinoma tumorigenesis by regulating the levels of hsa-miR-494 and the expression of CXCR4, HIF1A, ZEB1, SDC1, and TWIST132." (PMID 33707417, 2021). "In pancreatic adenocarcinoma (PAAD), circ-UBAP2 promotes M2 polarization of TAMs by targeting CXCR4 and ZEB1, which enhances tumor proliferation." (PMID 40296917, 2025). "In pancreatic adenocarcinoma (PAAD), the circ_0003945/miR-494 axis regulated PAAD progression by CXCR4 and ZEB1, key mediators of tumor immune cell infiltration." (PMID 38711855, 2024). "CircUBAP2 (hsa_circ_0007367) was shown to repress antigen presentation and induce immune escape in pancreatic adenocarcinoma (PAAD) through sponging miR-494 to upregulate CXCR4 and ZEB1 proteins, then leading to increased expression of CTLA-4 and PD-1." (PMID 38177102, 2024). "It was identified that the expressions of CXCR4, HIF1A, ZEB1, and SDC1 in pancreatic adenocarcinoma (PAAD) were controlled by circ-UBAP2 and miR-494." (PMID 32665846, 2020). "In pancreatic adenocarcinoma (PAAD), circ-UBAP2-hsa-miR-494 potentially targets CXCR4 and ZEB1 transcripts." (PMID 32943996, 2020).
sarcoma (12 papers, 2016 to 2023). A usually aggressive malignant neoplasm of the soft tissue or bone. "Sarcoma has a mesenchymal origin, and its mesenchymal phenotype is maintained by the functions of EMT-TFs, including TWIST1, SNAIL, SLUG, ZEB1 and ZEB2, and associated with more aggressive behaviors." (PMID 34022967, 2021). "The expression levels of ZEB1 protein in human sarcoma tissues are also positively correlated with lung metastasis, which is consistent with the finding showing that ZEB1 knockdown in MG-63 cells significantly inhibits cell invasive capability." (PMID 34022967, 2021). "On one hand, GRHL2 directly suppresses the expression of the EMT inducer ZEB1 in breast, ovarian, bladder cancers, and sarcoma." (PMID 32974388, 2020). "It has been reported that UC of the pancreas expressed epithelial-mesenchymal transition (EMT) markers (e.g. Slug, Twist, Zeb1), as in anaplastic carcinoma of the thyroid and sarcoma." (PMID 33004032, 2020). "In sarcomas, signaling pathways including the MAPK/ERK, Wnt/β-catenin, TGF-β and PI3K/Akt, EMT transcription factors ZEB1/2, SLUG, SNAIL, and TWIST1 promote migration, invasion, and metastasis." (PMID 35145908, 2021). "Except for sarcoma and HCC 1395 cells, carcinoma cells with upregulation of both Snail and ZEB1/2 are not so frequently observed." (PMID 35451213, 2022).
serous ovarian cancer (12 papers, 2013 to 2025). "Previous study has shown that lncRNA AP000695.4 promotes epithelial-to-mesenchymal transition in serous ovarian cancer by competitively binding miR-101-3p to regulate ZEB1 expression." (PMID 39416790, 2024). "ZEB1 was analysed in a meta-survival analysis of publicly available gene expression data from high-grade serous ovarian-cancer patients." (PMID 35794446, 2022). "High ZEB1 gene expression (HR = 1.31, n = 2051, p = 1.31e−05) is a marker of poor overall survival in high-grade serous ovarian-cancer patients." (PMID 35794446, 2022). "High gene expression of ETAR/ILK/YAP/AP-1/ZEB1 was a strong predictor of poor clinical outcome in serous ovarian cancer patients, indicating the translational relevance of this signature expression." (PMID 35477522, 2022). "High gene expression levels of ZEB1 are predictive of poor overall survival in high-grade serous ovarian-cancer patients." (PMID 35794446, 2022). "LncRNA PTAR was reported to promote EMT and metastasis in serous ovarian cancer by competitively binding miR-101-3p to regulate ZEB1 expression." (PMID 32039833, 2020). "LncRNA PTAR accelerates epithelial–mesenchymal transition and cell invasion–metastasis in serous ovarian cancer via sponging with miR‐101‐3p to modulate the expression of ZEB1." (PMID 32239639, 2020). "For example, lncRNA PTAR promoted EMT and invasion- metastasis in serous ovarian cancer by competitively binding to miR-101-3p to regulate ZEB1 expression." (PMID 31761783, 2019). "Previous studies have linked miR-101-3p to EMT inhibition, for instance, by targeting ZEB1 and affecting FN1 expression in serous ovarian cancer." (PMID 41382114, 2025). "In ovarian serous adenocarcinoma cells, the expression of VASH2 was inversely correlated with that of miR-200b, which represses the expression of ZEB1 and ZEB2, the products of which are key to epithelial-to-mesenchymal transition." (PMID 23426782, 2013). "In contrast, in this study we found that ZEB1 gene expression is not predictive of survival in high-grade serous ovarian-cancer patients confirmed to be treated with platinum chemotherapy." (PMID 35794446, 2022). "In contrast, ZEB1 is not predictive of overall survival in high-grade serous ovarian-cancer patients known to be treated with platinum chemotherapy." (PMID 35794446, 2022).
clear cell renal cell carcinoma (11 papers, 2016 to 2023). "For example, SNHG5 mediates miR-205-5p, which targets zinc finger E-box-binding homeobox 1 to promote the progression of clear cell renal cell carcinoma." (PMID 35346361, 2022). "In clear cell renal cell carcinoma, Cripto-1 promoted EMT properties, including the down-regulation of E-cadherin and the up-regulation of Vimentin, N-cadherin, ZEB-1, and Snail." (PMID 34434900, 2021).
squamous cell carcinoma (11 papers, 2016 to 2024). A carcinoma arising from squamous epithelial cells. "In squamous cell carcinoma, EMT is associated with downregulation of E-cadherin (epithelial cadherin, E-cad) and upregulation of TWIST, ZEB, and zinc finger E-box-binding homeobox 1 (ZEB1)." (PMID 36250005, 2022). "We detected P-STAT3, ZEB1, and Twist1 in squamous cell carcinoma tissues and adjacent tissues by immunohistochemistry." (PMID 33363013, 2020). "Here, the authors report that intracellular activation of thyroid hormone by the D2 deiodinase enzyme promotes invasion and progression of squamous cell carcinoma by transcriptionally up-regulating ZEB-1." (PMID 31776338, 2019). "Additionally, signaling cross-talk in squamous cell carcinoma involving NOTCH1 with the transforming growth factor beta (TGF-β) pathway represses NOTCH3 through zinc finger E-box binding homeobox 1 (ZEB1) and promotes EMT and tumor initiation." (PMID 33322834, 2020). "We subsequently analyzed the relationship between FSTL1 and ZEB1 in other squamous carcinomas in the TCGA and GTEx data, and the data show that FSTL1 and ZEB1 expression are linearly correlated in these tumors." (PMID 38605354, 2024). "Indeed, in squamous cell carcinoma, NOTCH1 induces the expression of Zinc finger E-box-binding homeobox 1 (ZEB1), a transcription factor that acts as a negative regulator of Notch3 gene expression." (PMID 32908186, 2020).
diabetes (10 papers, 2015 to 2025). "The DM VitDD group presented an increase in ZEB1 gene expression at 12 weeks (P = 0.04) after diabetes induction compared to Ctrl VitDD and DM VitD groups." (PMID 37391399, 2023). "Previous studies have verified that under the circumstance of diabetes, downregulated miR-192 in the proximal tubular cells enhances the expression of ZEB1, thereby activating the TGF-β-mediated downregulation of E-cadherin." (PMID 37686366, 2023). "The TXNIP/miR-200/Zeb1/E-cadherin signaling pathway links miR-200 to beta cell apoptosis and diabetes and links TXNIP to inhibition of epithelial-mesenchymal transition (EMT), a process involved in beta cell expansion, predicting its decline." (PMID 35903753, 2022). "We found that Zeb1 is involved in the maintenance of tissue homeostasis and protects the pancreas from accelerated tissue damage during metabolic disorders, like diabetes mellitus." (PMID 34112759, 2021). "TF prediction analysis showed that NR3C1, TEAD and TFs that cooperate with YAP-TEAD, such as Klf4, SP1, AP1, MYC and ZEB1, were enriched in the DEGs of the diabetes vs. control comparison." (PMID 34970541, 2021). "How Zeb1 is integrated in the complex regulation of diabetes, sex steroids, fatty liver, increase of visceral fat and pancreas steatosis still remains obscure." (PMID 34112759, 2021). "Engineered EVs—acting on endoplasmic reticulum regulation, ZEB1 and possibly on Wnt/β-catenin and PI3K/AKT pathways—effectively enhanced osteogenesis and neoangiogenesis in diabetic osteopathy." (PMID 41511311, 2025). "Our findings demonstrate the key role of ZEB1 in EMT in cultured BCD cells, and suggest that ZEB1 inhibition may contribute to protocols of BCD cell redifferentiation, aimed at generating functional human β-like cells for cell therapy of diabetes." (PMID 26264186, 2015).
keratoconus (10 papers, 2013 to 2025). A degenerative, structural disorder of the eye, characterized by a cone-shaped protrusion of the cornea. "We present the clinical case of a woman with PPCD and keratoconus, with a previously undescribed mutation in the ZEB1 gene." (PMID 36613650, 2022). "Keratoconus is a progressive corneal disorder that may be associated with genetic factors, and new pathogenetic variants of ZEB1 and ZNF469 were identified in this study." (PMID 40547359, 2025). "A large proportion of variants in ZEB1 caused PPCD, while a small proportion of variants in ZEB1 caused FECD, and variant c.1920G>T, p.(Gln640His) caused CD co-existing with keratoconus." (PMID 36902444, 2023). "It has been suggested that a missense substitution in the ZEB1 protein are associated with FECD and keratoconus." (PMID 36292595, 2022). "The genetic risk factors have been researched genome-wide, among which the corneal dystrophy genes ZEB1 and TGFb1 are considered to be related to keratoconus." (PMID 33923743, 2021). "This is the first case reported in the literature, in which keratoconus, EBMCD and FECD are present in the same patient and are related to ZEB1 gene mutations." (PMID 33923743, 2021). "In addition to ZEB1, variations in the ZNF469 gene have been implicated in keratoconus pathogenesis." (PMID 40547359, 2025). "Variations of ZEB1 and ZNF469, which are identified in corneal dystrophy, have been suggested to be related to keratoconus." (PMID 40547359, 2025). "Other candidate genes including SOD1, ZEB1, TGFB1, FLG, interleukin, and collagen may have a role to play in the pathogenesis of keratoconus and need further elucidations." (PMID 25254113, 2014).